ALG3 (ALG3 alpha-1,3- mannosyltransferase)
Diseases named in the same sentence as ALG3 in open-access papers (continued):
Sharing a sentence is not in itself a finding about the gene and the disease.
cancer (continued). "Recently, increasing evidence has revealed that ALG3 overexpression promotes carcinogenesis, tumor proliferation, metastasis, and radio resistance and impairs antitumor immunity in several cancers." (PMID 38022516, 2023). "Second, a previous study has reported that ALG3 can affect the proliferation of BRCA, OSCC, and NSCLC, indicating that ALG3 can affect the proliferation of some cancer cells." (PMID 35782861, 2022). "Elevated α1,3-mannosyltransferase 3 (ALG3), which catalyzes the α1,3-mannosylation of glycoproteins, has been found in some malignant tumors." (PMID 36231102, 2022). "ALG3 promotes cancer cell stemness and decreased radioresistance of BC patients by regulating N-linked glycosylation of TGF-β receptor II." (PMID 35444644, 2022). "First, we discovered that ALG3 was highly expressed in several malignant tumors, and high expressions can affect the prognosis of patients." (PMID 35782861, 2022). "IHC results showed the abnormal expression of ALG3 was positively correlated with the advanced histologic grade and cancer stage." (PMID 35782861, 2022). "In short, our results suggested that ALG3 was overexpressed in different cancers including liver hepatocellular carcinoma tissues and liver cell lines." (PMID 35782861, 2022). "Researchers have observed that ALG3 contributes to high mannose-type N-glycans in several cancers, and mannose-type N-glycan upregulation has been shown to be related to cancer progression." (PMID 35782861, 2022). "The tumor and non-tumor tissues were notably in different degrees of staining, and ALG3 staining was stronger in advanced-grade versus early-grade carcinoma." (PMID 35782861, 2022). "Mechanistic investigation showed that ALG3 promoted radioresistance and cancer stemness by inducing glycosylation of TGF-β receptor II (TGFBR2)." (PMID 33931075, 2021). "Mechanistically, our results further revealed ALG3 promoted radioresistance and cancer stemness by inducing glycosylation of TGF-β receptor II (TGFBR2)." (PMID 33931075, 2021). "To determine the optimal cutoff value for ALG3 protein expression in cancer cells, we conducted an analysis using the MaxStat package in R. The results indicated that patients were divided into high ALG3 expression group (>60, n = 75) and low expression group (≤60, n = 104)." (PMID 40475760, 2025). "In this research, we conducted a pan-cancer analysis to examine the link between ALG3 expression, patient prognosis, immunological milieu, microsatellite instability (MSI) immune checkpoint genes, tumor mutation burden (TMB), and immunological neoantigens in 33 cancers." (PMID 38329424, 2024). "This prompted us to infer that ALG3 has potential prognostic significance in some types of cancers." (PMID 38329424, 2024). "Therefore, our research aims to investigate ALG3 by a pan-cancer investigation of the integrated multi-database." (PMID 38329424, 2024). "We performed a pan-cancer assessment on ALG3 utilizing datasets from The Cancer Genome Atlas (TCGA) and Genotype-Tissue Expression (GTEx) to examine its tumor-related roles across malignancies and its link to particular molecules and cells in the tumor microenvironment (TME)." (PMID 38329424, 2024). "ALG3 was strongly expressed in cancer tissues compared to paraneoplastic tissues." (PMID 39287231, 2024). "We chose TIMER2.0 and HPA cancer databases to investigate the expression of ALG3 mRNA." (PMID 35782861, 2022). "Importantly, the ALG3 expression based on tumor grade and cancer stage performed significant differences." (PMID 35782861, 2022). "Importantly, both attenuation of glycosylation using tunicamycin and inhibition of TGFBR2 using LY2109761 differentially abrogated the stimulatory effect of ALG3 overexpression on cancer stemness and radioresistance." (PMID 33931075, 2021). "Upregulating ALG3 enhanced radioresistance and cancer stemness in vitro and in vivo." (PMID 33931075, 2021).
cancer (continued). "Furthermore, in nude mice injected with MCF-7 cells, the removal of ALG3 from the cancer cells reduced both tumor development and HSF2 levels, which indicates a positive feedback between ALG3 and HSF2." (PMID 32408596, 2020). "According to the findings of this research, ALG3 is a major contributor to the onset and progression of a wide variety of cancer types, and the targeted suppression of ALG3 could be a useful method for treating cancer." (PMID 38329424, 2024). "Here we show that ALG3 is phosphorylated downstream of the PI3K/AKT pathway in both growth factor-stimulated cells and PI3K/AKT hyperactive cancer cells." (PMID 40236010, 2025). "For instance, ALG3 was found to hinder CD8+ T cell infiltration by suppressing chemokine secretion, affecting 5-fluorouracil sensitivity in various cancers and presenting novel therapeutic targets." (PMID 39861138, 2025). "This is consistent with the finding that inhibition of ALG3 leads to induction of the unfolded protein response, ER stress, and impaired cell proliferation in PI3K/AKT hyperactive cancer cells." (PMID 40789468, 2025). "Additional studies found that ALG3 suppresses CD8+ T cell infiltration by inhibiting chemokine secretion, impacting the efficacy of 5-fluorouracil in cancer therapy." (PMID 39861138, 2025). "The correlation of ALG3 expression with overall survival (OS) and disease-free survival (DFS) was calculated individually in 33 TCGA cancers utilizing univariate survival analysis." (PMID 38329424, 2024). "High expression of mannose transferase gene ALG3 can enhance proliferation, migration, and EMT ability, as well as stemness of cancer cells." (PMID 35265520, 2022). "Previous studies have reported that cancer stem cells significantly contribute to the development of radioresistance in cancer scenario, and OCT4 intensity was significantly upregulated in ALG3-overexpressing tumor tissues from the mice." (PMID 33931075, 2021). "In this research, we discovered that ALG3 is capable of efficiently activating all 6 distinct kinds of immune cells (neutrophils, CD8+ T cells, macrophages, CD4+ T cells, dendritic cells, and B cells) in approximately 20 different types of cancer." (PMID 38329424, 2024). "Indeed, several glycosylation factors, namely ALG8, ALG3, COLGATLT1, B4GALT3 and DPM2, show increased expression levels in these and other cancers." (PMID 36009354, 2022). "We focused our attention on determining the significant role that ALG3 plays in the progression of a variety of malignancies by meticulously examining the data that was gathered from the GTEX and CCLE databases from a large number of cases of diverse kinds of cancer." (PMID 38329424, 2024).
tumor (19 papers, 2014 to 2025). "Kaplan-Meier survival analysis showed that high ALG3 expression in tumor cells and TIICs was significantly associated with poorer prognosis." (PMID 40475760, 2025). "Further clinical correlation analysis reveals that high ALG3 expression is significantly associated with tumor size, tumor stage, microvascular invasion (MVI), and clinical staging, all of which are key predictors of HCC progression and prognosis." (PMID 40475760, 2025). "Based on these findings, it is conceivable that ALG3 is implicated in the production of tumor-initiating cells and has a connection to the development of drug resistance in tumors." (PMID 38329424, 2024). "The result showed that the expression of ALG3 was shown to be positively linked to tumor neoantigen in LUAD and THYM." (PMID 38329424, 2024). "ALG3 (Asparagine-Linked Glycosylation 3) is a key enzyme involved in the N-glycosylation process that affects protein glycosylation and plays an important role in tumor cell survival and immune microenvironment regulation." (PMID 40475760, 2025). "Importantly, ferroptosis induced by ALG3 inhibition exhibits distinct immunogenic characteristics, including the release of damage-associated molecular patterns that promote anti-tumor immune responses." (PMID 41008983, 2025). "Moreover, the expression of ALG3 in tumor-infiltrating immune cells (TIICs) was also significantly associated with tumor number (P ≤ 0.0001), CNLC stage (P = 0.022), and TNM stage (P = 0.027)." (PMID 40475760, 2025). "ALG3 appears to be intimately associated with tumor development in the TME." (PMID 38329424, 2024). "Furthermore, our research found that KEGG enrichment, single-cell RNA and spatial sequencing analyses were effective in identifying key signaling pathways in ALG3-associated tumor growth." (PMID 38329424, 2024). "We also analyzed the association between ALG3 expression level and tumor neoantigen." (PMID 38329424, 2024). "The findings implicated that ALG3 expression was related to the tumor microenvironment." (PMID 38329424, 2024). "Treatment with tunicamycin, a broad N-glycosylation inhibitor that affects multiple steps in the pathway, including ALG3-dependent processes, produces effects similar to those of ALG3 deletion, suggesting that general N-glycosylation deficiency can promote ferroptosis-mediated tumor suppression." (PMID 41008983, 2025). "In the univariate Cox regression analysis of 180 patients, high ALG3 expression in tumor cells, stromal cells, tumor number, tumor size, MVI, CNLC stage, and TNM stage was significantly associated with overall survival (OS)." (PMID 40475760, 2025). "Further analysis revealed that high ALG3 expression was associated with reduced infiltration of CD8+ T cells and CD68+ macrophages in both tumor and stromal areas, while positively correlating with increased infiltration of FOXP3+ regulatory T cells (Tregs)." (PMID 40475760, 2025). "Further multivariate analysis confirmed that high expression of ALG3 in both tumor cells and stromal cells was an independent poor prognostic factor for OS." (PMID 40475760, 2025). "Pearson’s χ2 test revealed that high expression of ALG3 in tumor cells was significantly correlated with tumor number (P = 0.032), tumor size (P = 0.026), microvascular invasion (MVI) (P = 0.029), TNM clinical stage (P = 0.027), and CNLC stage (P = 0.014)." (PMID 40475760, 2025). "The TKI (Tumor Killing Index) values for the anti-PD-1 group from the PDOTs cohort were ranked in descending order, and it was observed that patients with high ALG3 expression were predominantly clustered in the lower TKI value regions." (PMID 40475760, 2025).
tumor (continued). "First, bioinformatics analysis of HCC-related data from the TCGA database was performed to investigate ALG3 expression patterns in tumor tissues and its correlation with clinical features." (PMID 40475760, 2025). "We discovered that ALG3 was expressed in monocytes or macrophages, oligodendrocytes, and particularly in tumor cells exhibiting considerably elevated expression levels." (PMID 38329424, 2024). "ALG3 overexpression results in glycoprotein malfunction, which promotes tumor cell proliferation and invasion." (PMID 38329424, 2024). "Multivariate analysis indicated that ALG3 expression, tumor number, and tumor size were the independent factors of 5-year overall survival." (PMID 35782861, 2022). "In non-small-cell lung cancer (NSCLC), the expression of ALG3 in tumor tissues was significantly increased compared with that of normal tissues." (PMID 35774357, 2022). "The results showed that ALG3 was significantly overexpressed in HCC tissues compared with non-tumor adjacent tissues." (PMID 35782861, 2022). "And the effect of ALG3 on tumor growth after IR was verified in an orthotopic xenograft tumor models." (PMID 33931075, 2021). "Consistently, tumor volumes and weight in the ALG3-sg group were significantly suppressed after radiation treatment." (PMID 33931075, 2021). "We observed that upregulation of ALG3 significantly promoted tumor growth rate of MCF-7 and ZR-75-30 compared with the vector group." (PMID 33931075, 2021). "ALG3 silencing significantly suppresses tumor growth and downregulates HSF2 expression, suggesting the presence of a feedback loop between these two genes." (PMID 35087869, 2021). "Conversely, it was also demonstrated in the basal-like TNBC cell lines that upon ALG3 knockout models, previously radioresistance cell lines were sensitized, tumor growth in vivo was delayed and OCT4 expression was decreased." (PMID 34680503, 2021). "To find out if ALG3 have a stronger predictive ability in a particular tumor type, we perform the subgroups analysis based on tumor type." (PMID 33931075, 2021). "The immunohistochemical (IHC) staining showed that ALG3 expression was dramatically higher in radioresistant compared with radiosensitive tumor tissue at the end of the experiment." (PMID 33931075, 2021). "The IHC staining showed that ALG3 expression was reduced in more ALG3-sg tumor tissues than relative to in the vector tumors tissues at the end of the experiment." (PMID 33931075, 2021). "We found that ALG3 significantly increased tumor volume and weight compared with the vector group after radiation treatment." (PMID 33931075, 2021). "The expression levels of ALG3 in tumor cells and stromal cells were positively correlated with the abundance of CD4+ FOXP3+ regulatory T cells (Tregs), CD3+CD4+ T cells and PD-L1, whereas they were negatively correlated with the abundance of CD8+ T cells and CD68+CD86+ macrophages." (PMID 40475760, 2025). "By affecting the function of M1 macrophages, ALG3 may contribute to immune escape and immune suppression within the tumor, providing a potential therapeutic target for overcoming immune evasion." (PMID 40475760, 2025). "The results showed that the expression level of ALG3 protein in tumor cells (56.71 ± 19.12) was significantly higher than in normal epithelial cells (43.87 ± 16.50, P < 0.001), and the expression level of ALG3 in HCC tissues was notably higher than in benign tissues." (PMID 40475760, 2025). "Notably, in HCC samples, paired sample analysis was performed to compare the expression levels of ALG3 between tumor tissues and normal tissues, showing a significant upregulation of ALG3 in tumor tissues (P < 0.001)." (PMID 40475760, 2025). "A high ALG3 expression level may promote tumour proliferation, metastasis, and metabolic reprogramming." (PMID 38556542, 2024). "In addition, ALG3 modulates tumour immunogenicity through various pathways and is believed to be a therapeutic target to enhance the efficacy of ICIs34." (PMID 38556542, 2024).
tumor (continued). "ALG3 has significant modulatory function in the process of tumor development." (PMID 38329424, 2024). "All of these findings indicate that ALG3 could promote tumor growth by increasing MSI and TMB via the mechanism of modulating genes involved in mismatch repair." (PMID 38329424, 2024). "In tumor cells, ALG3 is involved in the production of high-mannose type N-glycans." (PMID 38329424, 2024). "Tcm and mast cells are closely related to tumorigenesis, suggesting that ALG3 might participate in tumor progression by regulating these immune cells; however, the underlying mechanism needs to be explored further." (PMID 36575396, 2022). "Radioresistant tumor tissues have a higher level of Ki67 expression and showed a significant lower caspase-3 activity, which indicated that both the apoptosis and proliferation process were involved in ALG3 induced radioresistance." (PMID 33931075, 2021). "ALG3 contributes to high-mannose type N-glycans in tumor cells." (PMID 33931075, 2021). "Moreover, ALG3 knockdown reduces tumor growth and HSF2 expression levels, indicating a feedback loop between HSF2 and ALG3." (PMID 34917120, 2021). "Therefore, ALG3, by enhancing Treg cell infiltration, may suppress anti-tumor immune responses, promoting HCC progression." (PMID 40475760, 2025). "However, high expression of ALG3 may suppress the function of CD68+CD86+ macrophages or reduce their recruitment in the tumor microenvironment, thereby weakening the anti-tumor immune response." (PMID 40475760, 2025). "Furthermore, ALG3 protein expression in tumor cells was significantly higher than in tumor stromal cells (40.98 ± 16.97, P < 0.001), suggesting that ALG3 may play an important role in the initiation and progression of HCC." (PMID 40475760, 2025). "ALG3 may influence macrophage polarization, potentially promoting the recruitment of M2 macrophages, which are involved in immune suppression, aiding tumor immune escape, and facilitating tumor growth and metastasis." (PMID 40475760, 2025). "As several lines of evidence have demonstrated the critical role of TGF-β pathway in the maintenance of tumor stemness and ALG3, another ALG family member, has recently been reported to enhance TGFBR2 glycosylation, we wondered whether ALG10 held the similar effects on TGFBR2 with ALG3." (PMID 35680565, 2022). "Moreover, OCT4 intensity was also upregulated in ALG3-overexpressing tumor tissues." (PMID 33931075, 2021). "Moreover, we found that silencing ALG3 reduced OCT4 intensity in the tumor tissues from the mice." (PMID 33931075, 2021). "The results showed significant overexpression of ALG3 in HCC tissues, with high expression correlating significantly with poor tumor prognosis." (PMID 40475760, 2025). "The expression levels of key glycosyltransferases, such as B3GNT3, ALG3, and GALNT14, along with tumor GAG content and proteoglycan expression patterns, can guide patient stratification and therapeutic decision-making." (PMID 41008983, 2025). "Univariate analysis showed that ALG3 expression, histology classification, TNM stage (AJCC), tumor size, tumor number, vascular tumor emboli, serum AFP, and HBsAg were the potential independent prognostic factors for HCC patients." (PMID 35782861, 2022). "The top candidate metabolic drivers were PYCRL, ALG3 and NUDT1, which were correlated in at least seven of the ten tumour types." (PMID 27358048, 2016). "ALG3 may regulate OX40 through glycosylation modifications, thereby limiting T cell function, particularly in the highly immune-tolerant tumor environment of HCC." (PMID 40475760, 2025).
tumor (continued). "Considering the small sample size in TNBC group, the Kaplan–Meier survival curves suggested that ALG3 was a predictive factor independent of tumor types, but it had a better discrimination in TNBC patients." (PMID 33931075, 2021). "ALG1 and ALG3 classified the tumours as COX-2 positive or negative using experimentally determined cut-off thresholds (mean or median value of the score) while ALG2 based on arbitrarily determined cut-off value of 10%." (PMID 25269624, 2014). "We examined whether or not there was a link between the ALG3 genes and the stemness of the tumor, as estimated by DNAss and RNAss." (PMID 38329424, 2024). "Each of the three antibodies similarly differentiated between the COX-2 positive and negative tumours if either ALG1 or ALG3 were used for the evaluation of the expression of the protein within individual lesions (ALG1: 41.5%-48.8%; ALG3: 46.3%-48.8% of the COX-2 positive lesions)." (PMID 25269624, 2014).
infection (5 papers, 2013 to 2024). The state of being infected such as from the introduction of a foreign agent such as serum, vaccine, antigenic substance or organism. "In M. oryzae, ALG3-mediated N-glycosylation of effector Slp1 is critical for its activity during host infection." (PMID 36145458, 2022). "Conversion from incident to older infection status among these 7 algorithms occurred first for Alg3 (gp41 band ≤0.5), tightly followed by Alg3.1 (gp41≤1) and Alg5 (p24≤0.5), Alg6 (p17≤0.5), Alg14, Alg2 (gp120≤1) and finally Alg4 (p31 = 0)." (PMID 23990968, 2013).